DDX4 (DEAD-box helicase 4)
Diseases named in the same sentence as DDX4 in open-access papers (continued):
Sharing a sentence is not in itself a finding about the gene and the disease.
thalassemia (1 paper, 2023). An inherited blood disorder characterized by a decreased synthesis of one of the polypeptide chains that form hemoglobin. "The 12-year-old XIAP-deficient patient exhibited approximately twice as many DDX4+ cells (patient 6) as the 9-year-old MDS patient and the 7-year-old ß-thalassemia major patient with the lower value." (PMID 36766757, 2023). "The second 7-year-old ß-thalassemia patient (tissue was applied for the organ culture) displayed a markedly higher proportion of DDX4+ cells (patient 2) compared to the ß-thalassemia major patient mentioned earlier." (PMID 36766757, 2023). "Both the 7-year-old patients with thalassemia and the 12-year-old XIAP deficiency patient show the same difference between the DDX4+ and the PIWIL4+ cells, so it can be assumed that the SPG differentiation, including proliferation of the SPG, is already more advanced here." (PMID 36766757, 2023).
viral infection (1 paper, 2025). "Further, the role of DDX4 in regulation of type III IFN responses critical for control of viral infection at mucosal barriers, and also inhibited by SOCS1, remains unknown although it is likely to be promoted by DDX4 via a similar mechanism." (PMID 39620586, 2025). "A more comprehensive understanding of how DDX4 and other DEAD/H‐box helicases modulate IFN responses could open new therapeutic avenues for treating various human diseases, with potential applications beyond limiting viral infection." (PMID 39620586, 2025).
cancer (12 papers, 2016 to 2024). A tumor composed of atypical neoplastic, often pleomorphic cells that invade other tissues. "The current literature on DDX4 suggests that it plays a role in OC progression due to its influence on DNA damage checkpoints and association with cancer stem cell marker, CD133." (PMID 33374923, 2020). "Six genes were found to be implicated in cancer etiology/progression/clinical outcomes with high degree of certainty: MMP1, DDX4, TRPM3, DPP6, KCNA1, and MUC17." (PMID 32625238, 2020). "The DDX4 accelerates cell cycle progression by abrogating the G2 checkpoint when overexpressed in cancer cells, while the aberrant expression of LRSAM1 may be involved in the cancer pathology." (PMID 30380781, 2018). "Since Ddx4 acts as positive translational regulator of proteins involved in the cell cycle, these results support the hypothesis that Ddx4+ cells in EOC represent the cancer stem cell component capable of proliferating and differentiating under specific stimuli." (PMID 31261822, 2019). "DDX4 is another commonly modified protein in both the cell lines, which is ATP-dependent RNA helicase with proven essential roles in cell proliferation and migration, which is consistently localized with the mitotic apparatus in various blood-derived cancer cells." (PMID 30380781, 2018). "They found that while genes like PIWIL1, PIWIL2, PLD6 (Zucchini), and DDX4 (VASA) were expressed in some cancer cell lines, their expression alone was not enough to form functional piRNA-PIWI silencing complexes (piRISCs)." (PMID 39717847, 2024). "The expression of Ddx4 on these cells confirms their staminal condition; this potentially may be related to the activation of unknown molecular mechanisms, thereby driving pathological events in aged ovaries such as cancer, rather than merely guaranteeing an ovarian reserve with aging." (PMID 31261822, 2019).
tumor (10 papers, 2017 to 2026). "Germ cell markers (Ddx4, Sycp3) were significantly reduced in tumours, indicating the paucity of germ cells in these areas." (PMID 37564373, 2023). "Consistent with these trends in cell lines, DDX4 depletion compromised in vivo tumor development while its overexpression enhanced tumor growth even after cisplatin treatment in nude mice." (PMID 36653474, 2023). "Similar to the PGCs, this tumor cell population was positive for Oct4 and DDX4, indicative of PGC-like cells." (PMID 32218989, 2020). "In particular, FSH in association with valproic acid actively primes the in vitro growth of Ddx4+ cells with the formation of large cell clusters resembling tumor-like structures." (PMID 32847044, 2020). "In this tumor, the Ddx4+ cells appeared small and round (5 μm diameter) and expressed the pluripotency-related molecule SOX-2 as well as the primordial germ cell marker STELLA along with Ddx4." (PMID 31261822, 2019). "However, the physiological significance of DDX4 in oncogenesis and tumor progression remains poorly described." (PMID 36653474, 2023). "However, a high signal intensity of Ddx4 occurred also in stromal cells within the tumor microenvironment, in particular in several samples of invasive OCs grouped in A2." (PMID 32847044, 2020). "Notably, the similar PGC-like subpopulation of tumor cells expressing both Oct4 and DDX4 was also observed in liver micro-metastasis derived from both 4T1 and B16-BL6 tumors." (PMID 32218989, 2020). "This analysis provided evidence that intra-tumor Ddx4+ cells were already activated in their commitment to differentiate toward the mesenchymal lineage, especially when derived from the microenvironment of an advanced NS-EOC, compared to not metastatic OCs from the A1 subgroup." (PMID 32847044, 2020). "Thus, we explored the hypothesis that, in response to FSH stimulation, Ddx4+ OSCs differentiate to mesenchymal-like (ML) cells capable to regulate the tumor cell growth and aggressiveness by inflecting their transcriptome." (PMID 32847044, 2020). "Hence, in relation to such a suggested native proclivity toward a mesenchymal evolution, it is conceivable that the Ddx4+ cell enrichment in OC is related to the FSH-primed differentiation of OSCs to intra-tumor stromal cells, to sustain OC growth and expansion." (PMID 32847044, 2020). "Following cell fixation and permeabilization, Ddx4 was revealed by flow cytometry at high cytoplasmic levels in almost the entire A2780 cell population (96.2%), while a variable expression of the antigen was found by immunohistochemistry (IHC) in patient-derived tumor samples." (PMID 32847044, 2020). "Knocking out PGC specification inducers (ACVR1, SMAD5, PRDM1, or SOX17) or fate-maintaining genes (NANOG or DDX4) suppressed both SPLC and tumor initiation." (PMID 42291258, 2026). "Functional studies exploring the hormone sensitivity of CD133+/Ddx4+VSELs showed that, in response to FSH, such a population of OSCs undergoes active proliferation resulting in formation of large tumor-like clusters." (PMID 32847044, 2020).
infection (5 papers, 2018 to 2024). The state of being infected such as from the introduction of a foreign agent such as serum, vaccine, antigenic substance or organism. "Within these tubules, spotty fluorescent HEV-3b ORF2 staining was found to co-localize with DDX4-positive testicular cells, indicating the infection of germ cells." (PMID 38517709, 2024). "Notably, MAC was costained with DDX4, the molecular marker of spermatogenic cells, and the number of DDX4+ MAC+ spermatogenic cells significantly increased after infection." (PMID 37120617, 2023). "Seven days after injection, our immunostaining analysis demonstrated that mCherry expression did not co‐localize with the germ cell marker DEAD‐box helicase 4 (DDX4), indicating the absence of AAVDJ infection in this specific cell type." (PMID 38817099, 2024).
blood cancer (1 paper, 2023). "Based on previous studies, DDX4 has already been recognized as a potential molecular target for chemotherapy due to its involvement in regulating cell cycle progression in various somatic-derived blood cancer cells." (PMID 37298272, 2023).
DDX4 also shares sentences with these, for which no sentence is quoted: brain tumors (1 paper); cholera (1); Cryptozoospermia (1); cyst (1); embryonal carcinoma (1); fertility disorders (1); liver cancer (1); lung carcinoma (1); malignant germ cell tumor (1); prediabetes (1); promyelocytic leukemia (1); sarcoma (1); serous papillary adenocarcinoma (1); Sertoli Cell-Only Syndrome (1); testicular germ cell tumor (1); yolk sac tumor (1).